C6orf52 (chromosome 6 open reading frame 52)
Tractability: No criterion of Open Targets' tractability assessment is met for any kind of drug.
Gene: Protein-coding gene on chromosome 6 (10,671,418 to 10,694,797, reverse strand). Ensembl gene ENSG00000137434.
Subcellular location (Human Protein Atlas): Nuclear speckles; Intermediate filaments
Genetic constraint (gnomAD): Loss-of-function variants: 12 observed, 10.29 expected, observed/expected ratio (o/e) 1.17, 90% interval 0.74 to 1.79. The synonymous counts are far from expectation, so gnomAD's model fits this gene poorly and the ratio says little. Missense variants: 114 observed, 124.29 expected, observed/expected ratio (o/e) 0.92, 90% interval 0.79 to 1.07. Synonymous variants: 29 observed, 45.37 expected, observed/expected ratio (o/e) 0.64, 90% interval 0.47 to 0.87.
Homologues: Orthologues: chimpanzee C6H6orf52 (98% identical), macaque C4H6orf52 (93% identical), pig C6orf52 (67% identical), rat C17h6orf52 (47% identical).
Diseases named in the same sentence as C6orf52 in open-access papers:
C6orf52 is named in the same sentence as 1 disease in open-access papers, as found by Europe PMC text mining. Sharing a sentence is not in itself a finding about the gene and the disease.
C6orf52 shares sentences with these, for which no sentence is quoted: cancer (1 paper).